HIF1A (hypoxia inducible factor 1 subunit alpha)
Diseases named in the same sentence as HIF1A in open-access papers (continued):
Sharing a sentence is not in itself a finding about the gene and the disease.
tumor (continued). "Because of this essential role in oxygen dependent metabolism, HIF-1α plays central roles in a variety of pathophysiological conditions, such as cardiovascular disease, all forms of ischemic conditions, osteoarthritis and tumor biology." (PMID 36444297, 2022). "Tumour HIF-1α positivity correlated to unfavourable tumour characteristics." (PMID 35140341, 2022). "Therefore, the mechanisms that mediate the increase in HIF-1α levels in BM-MSCs under hypoxic conditions mimicking the tumor microenvironment, along with the mechanisms by which BM-MSCs regulate VEGF expression, must be investigated." (PMID 36230633, 2022). "Together, these results demonstrate that SETD7 may act as tumour suppressor by negatively modulating HIF-1α-, but this negative regulation may be impaired if LSD1 is also highly expressed/active." (PMID 35326563, 2022). "The indirect stabilization of HIF-1α by lactate also contributes to activation of the carbonic anhydrase 9 (CA9) gene, encoding the transmembrane protein of the family of carbonic anhydrases (CAIX), which maintains a constant acidic pH in the tumor tissue." (PMID 35205136, 2022). "HIF-1α, a Ca2+ sensitive factor, has been shown to be involved in tumor cell metastasis." (PMID 36187789, 2022). "Hence, breaking the positive feedback loop between lactate and HIF-1α represents a valuable “key” to preventing sEV production in tumor cells, thus benefiting tumor therapy." (PMID 36531060, 2022). "In addition, elevated levels of HIF-1α in PCa tumour biopsies have been found to correlate with reduced time to biochemical failure in men following radiotherapy suggesting increased treatment resistance." (PMID 36233505, 2022). "In benign endometrium, the increase in HIF1α protein and VEGFA protein and gene expression in post-hysterectomy samples compared to pre-hysterectomy samples indicates exposure of tissues to warm ischaemia intra-operatively, which was particularly evident in the functionalis glands and stroma." (PMID 35775066, 2022). "Similarly, simultaneous activation of NF-κB and HIF-1α can synergically enhance tumour development and metastasis formation." (PMID 36429126, 2022). "The HIF-1α pathway plays an important role in tumor metastasis and angiogenesis." (PMID 34976188, 2022). "S3A), our results show that HIF1A affects the epithelial cell state during tumor progression." (PMID 35867798, 2022). "HIF-1α plays a vital part in the initial and developing stages of tumor metastasis." (PMID 35464826, 2022). "Hypoxia can increase the progression of tumor cells via activation of HIF-1α." (PMID 36224606, 2022). "Thus, the overall characterization of tumor-related pathways was improved, now including also the HIF1A and the PI3K-Akt pathways in the pool of those affected." (PMID 35876890, 2022). "Collectively, these results show that pharmacological inhibition of USP25 leads to reduced HIF-1α activity specifically in PDAC tumor cells, which impairs their survival in the hypoxic tumor microenvironment, and subsequently leads to a reduction in PDAC tumor growth in vivo." (PMID 35440539, 2022). "Moreover, TGF-β-mediated connective tissue growth factor (CTGF) overexpression alters HIF-1α-dependent cellular metabolism in fibroblasts, thereby supporting tumor growth." (PMID 35884382, 2022). "Furthermore, immunostaining of tumors revealed GLUT1 up-regulation in hypoxic pockets, likely due to HIF1α signaling that promotes a glycolytic switch in the tumor." (PMID 35193955, 2022). "Abnormal angiogenesis is also stimulated by tumor-associated macrophages (TAMs), activation of (mTOR) complex 1 (C1), ERK1, STAT3, via HIF-1α ubiquitination, and the up-regulation of carbonic-anhydrase (CA) 9 gene expression, and DNA damage responses 1 (Redd1)." (PMID 35745875, 2022). "A research found that circ_03955 through miR-3662/HIF-1α Axis activation of the Warburg effect functions as a tumor promoter, which may provide a new perspective for PC treatment." (PMID 36285300, 2022).
tumor (continued). "Thus, inhibiting HIF1α expression can ameliorate dysregulated glucose metabolism, which can effectively prevent tumor progression in HCCs." (PMID 35884416, 2022). "Moreover, LOX can also promote the synthesis of HIF-1α protein by positive feedback, and the two factors synergize and regulate each other to promote tumor progression." (PMID 36419894, 2022). "The level of HIF1A has been correlated with tumor progression, metastatic spread and outcome." (PMID 37386584, 2022). "Hypoxic conditions inactivate PHDs, allowing HIF1A the opportunity to translocate to the nucleus and form a protein complex, which acts as a transcription factor for the genes critical to hypoxia response promoting tumor cell survival." (PMID 36552827, 2022). "Moreover, another miRNA that is identified as tumor suppressor when overexpressed is miR-142, which targets HIF-1a and limits the tumor growth and invasiveness." (PMID 36292753, 2022). "To determine whether HIF1α expression in the tumor microenvironment is related to CASQ2 overexpression, we checked HIF1α and cancer‐associated fibroblast markers, FSP1 and αSMA, after indirect culture with stromal WI‐38 fibroblasts." (PMID 34743414, 2022). "The IHS scores of HIF-1α in tumor tissue of mice could be ordered as group M > C > W > C+W (from top high to low)." (PMID 35693265, 2022). "Ascorbate therapy may increase the activity of HIF hydroxylases, decreasing HIF1-α action and reducing tumor development." (PMID 35745630, 2022). "Therefore, we believe that targeting the transcriptional activity of HIF-1α in tumor cells contributes to the establishment of an inflammatory microenvironment, which helps recruit cytotoxic immune effector cells." (PMID 35795658, 2022). "As a consequence, the inhibition of the HIF-1α pathway by ACCS is beneficial for tumor treatment." (PMID 35178457, 2022). "Notably, western blotting analysis was conducted on protein extraction from tumor samples and revealed significant blockage caused by TAK-242, PDTC, and YC-1 on the TLR4/NF-κB/HIF-1α signaling loop." (PMID 35464826, 2022). "Lactate also stimulates angiogenesis in human tumor cells by preventing the inhibition of prolyl hydroxylase domain proteins (PHDs), resulting in the hydroxylation and stabilization of IκB kinase β (IKKβ) and HIF-1α." (PMID 35205136, 2022). "In this review, we summarize the reprogramming of tumor metabolism involving HIF-1α/ERRα." (PMID 35800058, 2022). "High levels of HIF-1α correlate with tumor progression and poor patient outcome." (PMID 35626708, 2022). "Therefore, the overexpression of miR-143 decreased the expression of IL6, inhibiting at the same time HIF-1α and NF-κB P65 expression, thus affecting tumor growth." (PMID 35454102, 2022). "Together, these findings also support a more generalised model in which activated forms of KRAS or AKT directly and/or indirectly increase levels of YB-1 levels, which, in turn, promote an elevated HIF1α response and potentially other cytoprotective programmes required for tumour formation in vivo." (PMID 34294889, 2022). "Using ELISA technique, we detected a significant decrease in HIF-1α levels in the blood serum of mice receiving SXT treatment suggesting, at least in part, that SXT may exert anti-tumor activity by modulating HIF-1α-related signaling pathways." (PMID 35372052, 2022). "However, more recent studies have suggested the significance of HIF1α during tumor initiation and development." (PMID 35505422, 2022). "This study investigated the effect of Perftoran® on ICG/PDT efficacy in presence and absence of Perftoran®via evaluation of phototoxicity by MTT; hypoxia estimation by pimonidazole, HIF-1α/β by ELISA, and 17 miRNAs (tumor suppressors, oncomiRs, and hypoxamiRs) were analyzed by qPCR." (PMID 35370727, 2022).
tumor (continued). "Similarly, gefitinib and erlotinib reduced vessel formation, decreased vascular permeability, and improved tumor oxygenation in xenograft models through the inhibition of HIF-1α and the production of angiogenic factors such as VEGF-A and IL-8 by tumor cells." (PMID 35158804, 2022). "Mechanistically, enhanced aerobic glycolysis mediated by upregulation of HIF-1α and subsequently increased target glycolytic genes and decreased mitochondrial biogenesis was found to contribute to the promotion of tumor growth and metastasis by EDDM3A in GC cells." (PMID 35039478, 2022). "Notably, deletion of HIF-1α in mouse NK cells inhibits tumor growth despite reducing cytolytic activity of NK cells." (PMID 35185932, 2022). "Vit-C has been shown to suppress HIF1-α-dependent tumor growth." (PMID 35745630, 2022). "In addition to antiproliferative and proapoptotic effects, celastrol repressed tumor growth, angiogenesis, invasion, and metastasis through reduced hypoxia-induced accumulation of HIF-1α protein." (PMID 35444532, 2022). "Additionally, of 11 hypoxia-related gene-expression signatures from the literature, 10 correlated with HIF-1α protein level, and 5 with an increased risk of IBTR within 5 years after resection of the primary tumour." (PMID 35140341, 2022). "Additionally, knockout of Glut‐1 and/or HIF‐1α limited tumour growth, tumour volume and tumour weight compared with tumours in control mice." (PMID 35415942, 2022). "Hence, in this review, we present insights into the complexity of cellular metabolism, metastasis, tumor angiogenesis, and survival of cancer stem cells induced by HIF-1α." (PMID 36014432, 2022). "However, when tumor cells are hypoxic, HIF1α can inhibit the transcription of ODC by binding to MAX and inducing the binding of MAX-interacting protein (MXI1) with MAX." (PMID 35912204, 2022). "Furthermore, HIF-1α overexpression enhanced tumor development, vascularization, and energy metabolism, whereas a decrease in its activity had the opposite impact during in vitro xenograft tests." (PMID 36338690, 2022). "Although the mechanism underlying eIF5A and HIF-1α expression is yet to be elucidated, this regulation makes eIF5A an attractive therapeutic target because HIF-1α mediates the adaptive response in the hypoxic environment of tumor spheroids." (PMID 35163207, 2022). "Additionally, enriched signaling pathways other than HIF-1α/VEGFA should be investigated in tumor tissues after swimming." (PMID 35291563, 2022). "Increased tumor angiogenesis and drug resistance may be regulated differentially by HIF1α/2α and by oncogenic miRs, such as miR-155 and miR-210, that regulate pathways independent of HIFs." (PMID 35216330, 2022). "It is widely accepted that HIF-1α/VEGF signaling is essential for tumor angiogenesis." (PMID 35056404, 2022). "Multiple signals discussed in Section 4, such as NF-κB and HIF-1α, play central roles in tumor initiation and progression, suggesting that the nucleolus may constitute an oncogenic hub for tumor aggressiveness." (PMID 36230979, 2022). "Tumors in hypoxic environments activate the expression of a series of target genes through the induction of HIF-1α production, which ultimately affects tumor metabolism and angiogenesis and promotes increased proliferation, metastasis, migration, and invasion of tumor cells." (PMID 36139386, 2022). "Jiedu Sangen decoction(JSD) may inhibit glycolysis and reverse 5-FU resistance through PI3K/AKT/HIF-1α signaling pathway, thereby inhibiting glycolysis, inducing apoptosis, and enhancing anti-tumor activity." (PMID 36778600, 2022). "In addition to HIF-1α, the further work is required to explore the possible key point through which mediated glycolysis involved in docetaxel-mediated tumor glycolysis." (PMID 36536346, 2022). "SNPs in HIF1A are related to tumour mass, a major determinant of disease outcome." (PMID 34708297, 2022).
tumor (continued). "In addition, HIF-1α contribution to positive PD-L1 expression is ROS dependent and this accompanies the infiltration of tumor supportive immune cells, myeloid-derived suppressor cells (MDSCs), regulatory T cells (Treg), and tumor-associated macrophages (TAMs)." (PMID 36154922, 2022). "HIF-1α has been identified as a direct target of miRNAs in multiple tumor types." (PMID 36311748, 2022). "Moreover, HIF-1α silencing in MM cells has been shown to inhibit tumor progression due to decreased angiogenesis and bone destruction by the downregulation of proangiogenic and pro-osteogenic cytokines." (PMID 36231060, 2022). "Overall, the in vitro data on the GBM tumor cell line indicate that, in hypoxic conditions, high levels of p75NTR may correlate with high levels of HIF1A and KDM5C, a negative regulator of BDNF." (PMID 36142158, 2022). "The effect of HIF-1α and ERRα on tumor microenvironment remodeling and chemotherapy resistance in EC is not clear, and their interaction may be an important mechanism for EC cells to resist pyroptosis." (PMID 35800058, 2022). "The results showed that HIF-1α expression affected tumor proliferation." (PMID 35664561, 2022). "Induction of tumor progression by hypoxia/HIF-1α could occur using various mechanisms, including transcriptional and epigenetic mechanisms." (PMID 36461076, 2022). "HIF-1α promotes glycolysis and facilitates tumor progression." (PMID 35280516, 2022). "According to reports in the literature, the hypoxic environment stimulates the production of lactic acid in tumor cells by activating hypoxia-inducible transcription factor 1α (HIF-1α)-dependent genes such as glucose transporter 1 (GLUT1) and hexokinase 2 (HK2)." (PMID 35915188, 2022). "HIF-1α is highly expressed in proliferating endometrium nuclei, which is related to tumor invasion." (PMID 35800058, 2022). "When HIF-2α was expressed, HIF-1α was suppressed and tumour growth was increased.." (PMID 35572574, 2022). "The development of a SOCS5-specific inhibitor, an indirect inhibitor of HIF-1α, might be effective at controlling PM-induced tumor micrometastases during HCC resection." (PMID 36319626, 2022). "Our study demonstrates that CXCL10, a representative inflamed immune-response cytokine, activates CXCR3 in tumor cells to induce the phosphorylation of Src and the NF-κB subunit, p65, and the expression of HIF1-α in persistent EGFR-mutant tumor cells during EGFR-TKI treatment." (PMID 36612121, 2022). "However, there are still few studies on the effects of HIF-1α on the distribution of lipid metabolism and the reprogramming of lipid metabolism in tumor cells." (PMID 35800058, 2022). "Therefore, degradation of PML would increase HIF-1α content, thereby promoting a variety of HIF-1α-regulated metabolic reprogramming, migration, tumor growth and angiogenesis, etc.." (PMID 35847032, 2022). "However, in a recent single cell transcriptomic analysis, conditional deletion of HIF-1α in mouse tumor-infiltrating NK cells lead to increased NK cell activation, upregulated NF-kB signaling and improved anti-tumor activity." (PMID 35185932, 2022). "HIF-1α was found to stimulate tumour development via its impact on the cell cycle and apoptosis." (PMID 35328822, 2022). "Thus, activation of HIF-1α can promote the proliferation and enrichment of tumor stem cells, leading to treatment resistance." (PMID 36003773, 2022). "Therefore, tumor masses can show hierarchical tissue regions of decreasing oxygen concentration further into the tumor core, resulting in heterogeneous normoxic to necrotic tumor cells and, as a result, differential expression of HIF-1α and HIF-2α." (PMID 35267567, 2022). "In addition, it has been recently reported that HIF-1α can up-regulate the expression of PD-L1 in tumor-infiltrating macrophages, thereby promoting the immunosuppressive TME." (PMID 36226050, 2022).
tumor (continued). "Given the spatiotemporal regulation of HIFs, the isoforms may only be expressed at critical points in tumor progression; for example, HIF-1α primarily mediates angiogenesis, while HIF-2α mediates vascular integrity." (PMID 35267567, 2022). "Our study shows that the protumorigenic roles of HIF1A are both tumor cell intrinsic and extrinsic." (PMID 35867798, 2022). "Under hypoxia, tumors produce multiple oncogenic transformations in response to activated hypoxia-inducible factor-1 alpha (HIF-1α) signal, which promote tumor adaptation to hypoxia, such as metabolic adaptation, tumor microenvironment (TME) acidosis, distant metastasis and angiogenesis." (PMID 35413842, 2022). "Similarly, in hepatocellular carcinoma, lncRNA ROR accumulated in hypoxic tumor cell EVs was found to promote cancer growth by miR-145 downregulation and HIF1α stabilization." (PMID 35966580, 2022). "It has been demonstrated that the TACE procedure might upregulate the expression of hypoxia-inducible factor-1α (HIF-1α) and then activate the proangiogenic factors VEGF and PDGF, which are associated with early tumor recurrence and poor prognosis of HCC." (PMID 36776366, 2022). "However, transcriptional effects of HIF-1α have been reported in proliferating tumor cells (OXPHOS cells) even at >1% intracellular O2, contradicting the findings that FIH-1 regulates transcriptional activity even at low O2 (≥1% O2)." (PMID 35592530, 2022). "HIF-1α gene expression programs can help cells with energy metabolism, adapt to hypoxia stress, glycolysis, and metabolism, and control angiogenesis, erythropoiesis, tumor invasion, migration, and activation of protein genes related to tumor progression." (PMID 35664561, 2022). "Under normoxia, HIF-1α is upregulated in tumor cells in response to DOX as cancer therapy." (PMID 35340325, 2022). "Furthermore, the loss of biological activity of echinomycin following knockdown of Hif1a in E0771 provides genetic evidence that echinomycin confers an immunotherapeutic effect in vivo by targeting the HIF-1α in tumor cells." (PMID 35239514, 2022). "Energy for tumor cells is provided by the high activity of aerobic glycolysis stimulated by HIF-1α." (PMID 35800058, 2022). "Moreover, increased oxygenation decreases levels of tumor-protecting extracellular adenosine and reduces expression of HIF-1α dependent tumor-protecting proteins." (PMID 35360246, 2022). "HIF-1α is regulated mainly by oxygen homeostasis, but other factors can also influence its expression in tumor cells such as the activation of β1, β2, and β5 proteasomes, which are able to degrade HIF-1α and subsequently inhibit the expression of tumor-promoting genes." (PMID 36012159, 2022). "We specifically investigated whether expression of HIF-1α in the NKL cell line or the ex vivo expanded NK cells had any correlation with their anti-tumor cytotoxicity and cytokine-secreting functions." (PMID 34999917, 2022). "In HNSCC, the expression of HIF-1α has been shown to vary dependent on tumour location." (PMID 36077667, 2022). "Whereas hypoxia participates in carcinogenesis, resulting in less differenced tumor cells and poorer prognosis, HIF-1α could be predictive of the tumor response to treatment." (PMID 36358811, 2022). "While some studies have shown that hypoxia promotes mouse T cell cytotoxicity, there are also opposite reports showing that tumor hypoxia induces mouse T cell exhaustion and resistance to immunotherapy and depletion of HIF1α increases NK cell activity and tumor infiltration." (PMID 35840558, 2022). "Furthermore, the HIF-1α inhibition with echinomycin synergistically increased the immunotherapeutic effects of anti-CTLA-4 antibodies in mouse tumor models." (PMID 35805044, 2022).